IL13 (interleukin 13)
Diseases named in the same sentence as IL13 in open-access papers (continued):
Sharing a sentence is not in itself a finding about the gene and the disease.
infection (continued). "For those plasma cytokines and chemokines with no sex-specific differences over the course of infection, a majority, including IL-2, IL-10, IFN-γ, MIP-1α, IL-3, IL-4, IL-5, IL-12p70, IL-13, IL-17, and G-CSF, exhibited differing temporal patterns between genotypes." (PMID 35970557, 2022). "aureus human antibody responses in huNSG serum using our custom Luminex assay were undetectable 14 days post infection (data not shown), and serum cytokine levels analyzed over time revealed modest induction of human cytokines including IFN-γ, TNF-α, and IL-13." (PMID 33815412, 2021). "Importantly, in the absence of IL-13 expression, neither IL-4 nor IL-5 cytokine expression was changed in CD4+ T cells after infection." (PMID 34127548, 2021). "However, this study also provided evidence for the importance of the Th2 response in acute schistosomiasis, with antigen-specific Th2 (IL-4, IL-5 and IL-13), but not Th1 (IFNγ), CD4+ T cells at week 4 post infection, significantly correlated to acute symptoms." (PMID 33953712, 2021). "Furthermore, the unique pattern of IL-8, IL-13 and MCP-3, but not IL-4 expression was also recapitulated using experimental in vitro infection in PBMCs." (PMID 34215212, 2021). "In addition, we did not observe any secretion of IL-2, IL-10, IL-13, and IL-6 during an AIC infection." (PMID 31801841, 2019). "In addition, the relative level of several cytokines such as IL-5, IL-10, IL-7, IL-13 and Basic-FGF was not as impacted by the infection as the other chemokines/cytokines." (PMID 31391513, 2019). "Pretreatment of the infected rat models with doses of the traditional energy tonic (100 and 20 mg/mL/kg body weight) before infection nonsignificantly increased cytokines secretion (IL-1β, IL-2, IL-10, IL-13, IFN-γ, and RANTES), while others did not change when compared to those with infection only." (PMID 28408939, 2017). "The current study also identifies several factors, including IL-1α, MIP-1α, RANTES, IL-12(p40) and IL-12(p70) that are induced in aged mice but not young mice following infection (compared to PBS) and other factors, including IL-1β, IL-10, IL-13 and eotaxin that are specific to young mice." (PMID 27936166, 2016). "Because of the mild infection in the lungs of non-drug-treated/SeV-infected mice, an attenuated inflammatory response in BALF resulted in only IL-13 and IL-15 (out of the 32 tested) being significantly increased compared to PBS-inoculated control mice (P < 0.01)." (PMID 27589232, 2016). "Other cytokines were unchanged after infection (IL-2, IFN-γ, IL-5 and IL-13; data not shown)." (PMID 22024399, 2011). "Consistent with previous findings, our experiments showed that the dose of worms administered, irrespective of the infection regime, was positively correlated with the concentration of IL4 and IL13 produced by parasite antigen-stimulated MLNs, the concentration of anti-S." (PMID 18575588, 2008). "The IL-13 levels were not significantly different between the group of stunted children with STH infection and the group of normal-height children without STH infection (p = 0.010) and in stunted children with STH infection compared with normal-height children without STH infection (p = 0.022)." (PMID 38393122, 2024). "Our previous finding that IL-4 and IL-13 drive the proliferative expansion of tissue-resident macrophages was made in L. sigmodontis-infected C57BL/6 mice, and although we appreciated that some of the proliferating cells had BM origins, we failed to observe monocyte recruitment during infection." (PMID 36948193, 2023). "Previous studies infecting global IL-4Rα−/−, IL-4−/−, and IL-13−/−mice on a BALB/c background with the visceralizing parasite Leishmania donovani have shown that the T helper 2 cytokines, IL-4, and IL-13, play influential but not completely overlapping roles in controlling primary infection." (PMID 31475014, 2019).
cancer (237 papers, 2002 to 2026). A tumor composed of atypical neoplastic, often pleomorphic cells that invade other tissues. "Enhanced IL-13 cytokine signaling is central to allergic response and is implicated in PD and some forms of cancer." (PMID 38399441, 2024). "Direct interactions in the co-culture of Hep-2 or RK33 human cancer cells with THP-1 monocytes were associated with lower IL-13 production than in the corresponding indirect co-cultures in inserts." (PMID 39057050, 2024). "Supportively, the IL-13 pathway has been implicated in treatment resistance in several types of cancers." (PMID 39598436, 2024). "Excoriated pruritus can be an intolerable symptom in patients with cancer where Type 2 inflammation and its associated cytokines IL-4 and IL-13 play major roles in the pruritus." (PMID 38846700, 2024). "During the tumor initiation process, cancer cells release a range of growth factors, including TGF-β, IL-6, and IL-13, which play a crucial roles in the activation of fibroblasts into cancer-associated fibroblasts (CAFs)." (PMID 39697341, 2024). "Existing research suggests that IL-13 and its receptors are linked to the advancement of multiple cancer types." (PMID 38519926, 2024). "The IL-13 and IL-4 signalling pathways have also been implicated in cancer biology, which further highlights IL-13 as a well-validated therapeutic target." (PMID 37483614, 2023). "Interleukin-13 (IL-13) is a secreted immunoregulatory cytokine that is linked to inflammatory reactions and cancer pathogenesis." (PMID 37958629, 2023). "Despite differences in affinity for IL13Rα2, all of the IL13-variant CARs demonstrated effector activity when exposed to IL13Rα2-expressing cancer cells and recombinant IL13Rα2 antigen." (PMID 35939683, 2022). "C-Myc has been shown to act as a transcription factor that induces the transcription of genes encoding cytokines, including IL-2, IL-13 and IL-17C, in cancer cells." (PMID 35954273, 2022). "Several human cancer cell lines with varying expression of IL13Rα1 were used to evaluate relative effector activity of IL13 WT and IL13-variant CAR T cells." (PMID 35939683, 2022). "Elevated levels of IL4, IL13, or their receptors have been associated with poorer patient outcomes such as cancer progression, recurrence, or reduced survival." (PMID 34235145, 2021). "It is not difficult to find that related genes in the interleukin-4 and interleukin-13 signaling pathways have decreased activity in cancer samples, and their associations have also been disrupted." (PMID 32832545, 2020). "We found that interleukin-4 and interleukin-13 signaling pathways have discredited activity in cancer samples, and their associations have also been disrupted." (PMID 32832545, 2020). "This study found a significant direct association between higher serum IL-13 levels and cancer progression in NASH." (PMID 32283835, 2020). "IL-13 promotes homeostatic KC proliferation and survival, which is disrupted in IL-13-deficient mice, causing increased susceptibility to carcinomas." (PMID 32849572, 2020). "Although malignancy was associated with a difference in IL-13 responses against ESAT-6/CFP-10, IL-13 responses were still higher among contacts than controls after correcting for malignancy." (PMID 31849981, 2019). "Several studies have reported the influence of SNPs in IL13 on the risk of cancer, and a meta-analysis concluded that IL13 rs20541 polymorphisms contribute to susceptibility to cancer." (PMID 28537887, 2017). "SNPs in the IL13 gene have been reported to contribute to abnormal expression of IL-13 and modify susceptibility to cancer development." (PMID 28537887, 2017). "In the literature, there are few studies investigating the association of IL-13 haplotypes and susceptibility to cancers." (PMID 23108822, 2012). "CYP17-[C518T], and IL13-[Arg130Gln] were found to be associated with other cancer related variables, such as serum estrogen and IgE levels, respectively." (PMID 16672066, 2006).
cancer (continued). "Even though we used a wide panel of inflammatory cytokines, genetic instruments were not available for several additional cytokines that may be implicated in cancer, such as IL-13, IFN-gamma and CXCL13." (PMID 35012533, 2022). "It has been reported that receptors for IL4 and IL13 (IL4Rα or IL13Rα1) in several type of cancers is associated with poor prognosis and thus could be therapeutic targets of cancer treatment." (PMID 35207737, 2022). "Moreover, IL-4/IL-13 and their receptors have been also associated with apoptosis, chemosensitivity, and prognosis in various cancers." (PMID 33450900, 2021). "In addition, scRNA-seq revealed upregulation of several cancer-associated (Il-4/Il-13, Hsf1/HSP), oncogenic (TGFβ, NGF, FGF, MAPK) and self-renewal (Wnt, Notch) pathways in p63+/−;ErbB2 luminal cells and PIMECs per se." (PMID 34023861, 2021). "Potential effect of IL-4 and IL-13 (250 ng/mL, 24 h) on the expression of genes encoding proteins relevant for cancer development by facilitating angiogenesis (HIF1A and VEGFA), inflammation (PTGS2, NOS2, CCL2), and metabolic reprogramming (GLUT1, ODC1, NOS2) was evaluated." (PMID 32512917, 2020). "PTP1B silencing or treatment with Claramine, a PTP1B inhibitor, caused a significant decrease in IL-13-mediated adhesion, migration and invasion of IL13Rα2-expressing cancer cells by inhibiting the dephosphorylation of Src Tyr530 and consequently, the phosphorylation of Src Tyr419, AKT and ERK1/2." (PMID 32098194, 2020). "Transcriptional analysis of correlation patterns was conducted on clinical samples from CRC patients to reveal possible association between expression level of IL4, IL4Ra, IL13, and IL13Ra1 and that of representative mediators/markers associated with cancer development and progression." (PMID 32512917, 2020). "Gastrointestinal tract cancers are associated with IL-4 and IL-13 upregulation, which may facilitate cancer growth." (PMID 32512917, 2020). "Therefore, reducing either of these by targeting IL-13 could consequently reduce the risk of cancer." (PMID 30460209, 2018). "Specifically, we observed a significant decrease in the levels of MIP-1α, GM-CSF, IL-13, IL-6, IL-10, IL-5, IL-12p70, and IL-4 after SNS administration, all of which are associated with the severity of MMD symptoms and cancer prognosis." (PMID 41491244, 2026). "AM52.1CAR T cells produced pro-inflammatory cytokines, including macrophage inflammatory protein 1 beta (MIP-1β), interleukin (IL-8), interferon gamma (IFN-γ), tumor necrosis factor alpha (TNF-α), and IL-13, in response to STn-positive cancer cells." (PMID 40925376, 2025). "The secretion of anti-inflammatory cytokines, such as IL-6, IL-10, and IL-13, can promote cancer stemness and contribute to the development of therapeutic resistance." (PMID 40800581, 2025). "Over the past few years, IL-13 and its receptors have been identified as promising targets for cancer therapy, with the inhibition of IL-13-producing cells being investigated as a potential therapeutic strategy." (PMID 40247153, 2025). "In line with other types of cancer, poor disease-free survival (DFS) was linked to upregulated IL-13 expression in patients with PCa." (PMID 40247153, 2025). "Taken together, our findings suggest crosstalk between cancer cells and ILC2s, in which cancer cells stimulate ILC2s to produce IL-13, which in turn enhances their migratory and invasive properties." (PMID 40247153, 2025). "IL-4 and IL-13 play important roles in Th2 immune responses, metabolism, tissue regeneration, remodeling, cancer, learning, and memory." (PMID 40405976, 2025). "Mounting evidence indicates that C. sinensis infection drives Th2 immune responses and facilitates the production of the cytokines IL-13, TGF-β, IL-10 and IL-4, which have been implicated in promoting cancer stemness." (PMID 38285640, 2024).
cancer (continued). "IL-13 is an important cytokine that plays crucial role in multiple immunoregulatory processes, contributing to cancer progression, tissue injury, respiratory disease, innate and adaptive antiviral immune response, and immunosuppression." (PMID 38508309, 2024). "In particular, IL-13 has been explored in the treatment of cancer in the formulation of supercytokines." (PMID 39447666, 2024). "The shift from M1 to M2 is orchestrated by interleukins IL-4 and IL-13, secreted by various cells within the cancer ecosystem, including cancer cells themselves." (PMID 39676864, 2024). "Although research on SUMF2 in cancer remains limited, it was found to bind to IL-13 and independently inhibit IL-13 secretion in bronchial smooth muscle cells." (PMID 39104534, 2024). "Background/Objectives: Interleukin 13 receptor alpha 2 (IL-13Rα2) is a receptor with a high affinity for IL-13 and is involved in the progression of human cancers." (PMID 39598436, 2024). "It has also been shown that IL-13, by reducing the expression of cadherines, regulates the mobility of cancer cells." (PMID 39057050, 2024). "A future goal is to systematically characterize epigenetic changes that occur downstream of IL4/IL13 signaling in cancer cells." (PMID 38731867, 2024). "These combined features make IL-13 an attractive candidate for treating different pathological conditions from cancer to chronic inflammatory diseases." (PMID 39447666, 2024). "Type 2 immunity play a role in cancer initiation and progression, type 2 cytokines (e.g., IL-4 and IL-13) can inhibit the function of cytotoxic T cells, which limit the ability of T cell to eliminate cancer cells." (PMID 37925492, 2023). "Next, we investigated the involvement of SHN3 in cancer invasion and proliferation, before and after IL-13 treatment, in CRC KM12SM cells and GBM U251 and U87 cells." (PMID 37963919, 2023). "Altered distribution of acetylated-tubulin in response to IL-13 treatment has been reported previously in numerous cancer cell lines and other highly proliferative cells." (PMID 37943759, 2023). "Our study shows that inhibition of STAT3 phosphorylation significantly reduces the regulatory effect of IL13 on cancer cell stemness." (PMID 37534250, 2023). "At this stage it is also likely that the phenotype of M2 macrophages is additionally controlled by CD4+ T helper type 2 (Th2) cells that express IL-4 and IL-13, and counteract the Th1 cell responses, as observed in other cancers." (PMID 37638028, 2023). "Specifically, IL-4 and IL-13 have demonstrated induction of cancer apoptosis as well as anti-inflammatory and innate immune activation functions." (PMID 35924165, 2022). "In conclusion, IL13-mutein CAR T cells show improved selectivity for IL13Rα2-expressing cancer cells relative to IL13Rα1-expressing tumors." (PMID 35939683, 2022). "It seems equally possible that basophil-derived IL-4/IL-13 also favor tumorigenesis by diminishing Th1-like immunity that is better suited to contest the cancer." (PMID 36578500, 2022). "IL-13, described as an inhibiting inflammatory cytokine, participates in immune surveillance in cancer, inhibits cancer cell apoptosis, and promotes tumour growth." (PMID 36159866, 2022). "In blood cancers, CLL and AML, the production of IL-13 from cancer cells suppresses immune functions." (PMID 35557940, 2022). "Interleukin-13 (IL-13) during normal and pathological conditions particularly cancer plays a versatile role in regulating immune environment and responses as well." (PMID 35612318, 2022). "ILC2s inside malignant tumours also produce IL-13 to encourage tumour growth and metastasis in mouse models." (PMID 35557940, 2022). "It has been suggested that lung group 2 innate lymphoid cells (ILC2), which produce IL-5 or IL-13 in response to IL-25 and IL-33, suppress the lung metastasis of cancer cells." (PMID 34170380, 2022).
cancer (continued). "IL13 and its receptors have been evaluated as a possible therapeutic target in different diseases including various types of cancer." (PMID 35700185, 2022). "Recently, IL4 and IL13 have been considered not only target for inflammatory diseases but also the therapeutic target of cancer." (PMID 35207737, 2022). "Chimeric proteins composed of IL-13 or IL-4 with PE were invented to target human cancer cells expressing the corresponding receptors." (PMID 33450900, 2021). "Reactome aggregation analysis (FDR < 0.01) showed that the red target group was mainly associated with four pathways: IL-4 and IL-13 signaling, ESR-mediated signaling, PI3K/AKT signaling in cancer, and signaling by VEGF." (PMID 34394377, 2021). "The activation of IL4Rα/IL13Rα1 by IL4/IL13 stimulates JAK1/JAK2/JAK3-STAT6-mediated proliferation of cancer cells." (PMID 33419470, 2021). "IL-13Rα2 is a high-affinity binding protein for its ligand IL-13 and a cancer-testis antigen as it is expressed in the testis." (PMID 34201539, 2021). "IL-13 levels in patients’ plasma were significantly higher in all the three cancer patients compared with controls." (PMID 33450900, 2021). "Considering the cytokines produced in the TME, the role of the interleukin-4 (IL-4)/interleukin-13 (IL-13) cytokine-receptor system has shown significant influence on cancer cell survival, progression, and metastasis." (PMID 33804263, 2021). "We have investigated the mechanisms of cancer invasion and metastasis as well as the involvement of the IL-13/IL-13Rα2 axis in pancreatic cancer." (PMID 34201539, 2021). "Initially considered a decoy receptor, we and others have demonstrated beyond reasonable doubt that IL13Rα2 is also a functional receptor for IL-13 signaling transmission in cancer cells." (PMID 33917458, 2021). "The second antigen-binding domain binds another target, e.g., other antigen associated with cancer (CD19, CD38, HER2, EGFR, CEA, or IL-13R-a2), or a cancer-related ligand (IL-13, heregulin, VEGF)." (PMID 33482842, 2021). "IL-4 and IL-13 as well as their receptors are expressed in and play important roles for the progression of several different kinds of cancers." (PMID 33450900, 2021). "M2 macrophages, which exert an immunosuppressive phenotype by the secretion of anti-inflammatory cytokines (i.e., IL-4, IL-10, and IL-13), were the only pro-cancer immune cells that were higher in high-thermogenesis TNBC." (PMID 34071012, 2021). "Nevertheless, increasing activities of IL-4 and IL-13 in cancers such as lymphoma, breast, lung, colorectal, and oral squamous cell, as well as pancreatic have been found closely associated with tumorigenesis and metastasis." (PMID 33804263, 2021). "Taken together our data suggest a crosstalk between cancer cells and ILC2s, in which cancer cells trigger ILC2s to produce IL-13, which in turn sustains their migratory and invasive capacity, yet without affecting their proliferation rate." (PMID 33953160, 2021). "While IL-4, IL-5 and IL-13 have been documented to contribute to cancer growth and metastasis, a dual pro- and anti-tumorigenic role of IL-10 has been reported in recent literature, as reviewed elsewhere." (PMID 34012451, 2021). "On the other hand, M2 macrophages triggered by IL-4 and IL-13 are often used to facilitate cancer progression." (PMID 35493265, 2021). "The HMC3 cells were stimulated with a cytokine cocktail known to originate from cancer cells, that was comprised of interleukins IL-4, IL-13, IL-10, growth factors TGFβ1/TGFβ2, and chemokine CCL2." (PMID 34566949, 2021). "IL-4 and IL-13 contribute to cancer progression in various cancer types, and several mechanisms have been documented." (PMID 34769439, 2021).